PPARG (peroxisome proliferator activated receptor gamma)
Diseases named in the same sentence as PPARG in open-access papers (continued):
Sharing a sentence is not in itself a finding about the gene and the disease.
lung carcinoma (continued). "Interestingly, four of the seven recurrent PPARγ mutations have also been identified in other types of cancer, including lung cancer, kidney cancer, cutaneous melanoma, and diffuse glioma." (PMID 33716977, 2021). "PPARγ is a member of the nuclear receptor superfamily regulating lipid and glucose metabolism and has been widely studied for tumor associated cellular function in various cancers such as breast, colorectal, and lung cancer." (PMID 29137280, 2017). "A recent case-control study of 500 incidentlung cancer cases and 517 age and sex frequency-matched cancer-free controls suggestedthat PPARγ polymorphisms in Chinese smokers may contribute to the etiology of lung cancer." (PMID 18704200, 2008). "Several studies have implicated PPARγ in lung cancer as well." (PMID 17597835, 2007). "A study was conducted to assess how sumoylation of PPARγ regulates lipid metabolism and enhances tumor suppression in lung cancer cells." (PMID 41304753, 2025). "Overall, ALDH1A3 has been identified as a novel metabolic target of PPARγ that has therapeutic implications, and this regulatory pathway is crucial in restricting the growth of lung cancer cells." (PMID 41304753, 2025). "In this context, Hua and colleagues conducted a study to examine the regulatory connection between ALDH1A3 and PPARγ in the metabolism of lung cancer." (PMID 41304753, 2025). "A study investigated the role of PPARγ activation in lung cancer treatment through both in vitro and in vivo experiments, demonstrating its potential as a therapeutic target." (PMID 41304753, 2025). "PPARγ plays a central regulatory role in enhancing fatty acid synthesis and β-oxidation in lung cancer, and pioglitazone induces PPARγ activation and promotes de novo fatty acid synthesis and β-oxidation." (PMID 41304753, 2025). "The microarray dataset of 78 lung cancer cell lines revealed a substantial positive connection between PPARγ and ALDH1A3, a major enzyme involved in retinoic acid synthesis and NADH generation." (PMID 41304753, 2025). "Studies by Li and colleagues demonstrated that PPARγ activation has context-dependent effects in lung cancer, showing antitumor actions in cancer cells but pro-tumor effects in the tumor microenvironment." (PMID 41304753, 2025). "Molecular docking analysis was conducted to evaluate the binding affinities of the top 10 MQLEO-derived compounds against four lung cancer-associated targets (ESR1, CASP3, PPARG, and PTGS2)." (PMID 40573169, 2025). "Building on these findings, a Phase II clinical trial (NCT05919147) is currently investigating pioglitazone in lung-cancer patients with cachexia, positioning it as one of the few PPARγ agonists advancing into clinical evaluation." (PMID 41476922, 2025). "Studies have shown that PPARγ plays a critical role in halting lung cancer cell growth by interfering with the cell cycle." (PMID 41304753, 2025). "The study provides key insights into the role of sumoylated PPARγ in regulating lipid metabolism and tumor suppression by promoting lipid biosynthesis and β-oxidation in lung cancer cells." (PMID 41304753, 2025). "Although PPARγ activation in myeloid cells promotes lung cancer progression and metastasis, it remains a viable target for lung cancer treatment and prevention as monotherapy and in combination with traditional radiotherapy or chemotherapy." (PMID 40573305, 2025). "Several lines of evidence have shown that PPARγ is involved in cell cycle processes to induce the growth arrest of lung cancer cells." (PMID 38397426, 2024). "The combination of efatutazone (PPARγ agonist) with T0901317 resulted in the reduced proliferation of lung cancer cells via targeting the PPARγ/LXRα/ABCA1 pathway." (PMID 38550382, 2024). "Specifically, PPARγ induced PD-L1 degradation in malignant cells, which contributes to enhancing the sensitivity to immunotherapy, whereas PPARγ activation in myeloid cells promotes lung cancer progression and metastasis." (PMID 38397426, 2024).
lung carcinoma (continued). "Even so, PPARγ remains a viable target for the treatment and prevention of lung cancer due to the effectiveness of PPARγ agonists as monotherapy and in combination with traditional radiotherapy or chemotherapy in preclinical studies." (PMID 38397426, 2024). "Multiple studies have demonstrated that PPARγ activation exerts anti-tumor effects in lung cancer through regulation of lipid metabolism, induction of apoptosis, and cell cycle arrest, as well as inhibition of invasion and migration." (PMID 38397426, 2024). "PPARγ agonists have been demonstrated to exert anti-lung cancer effects by promoting cell differentiation, inhibiting cell proliferation, and inducing cell death." (PMID 38397426, 2024). "PPARγ-mediated lipid production in lung cancer cells leads to a significant increase in mitochondrial reactive oxygen species stress, which plays a crucial role in suppressing tumor growth." (PMID 38933330, 2024). "Subsequently, several clinical trials were launched to test the efficacy of PPARγ agonists in the treatment of lung cancer." (PMID 38397426, 2024). "This review aims to consolidate the molecular mechanism of PPARγ modulators and to discuss their clinical prospects and challenges in tackling lung cancer." (PMID 38397426, 2024). "Several studies have shown that PPARγ upregulates fatty acid synthesis and β-oxidation in lung cancer." (PMID 38397426, 2024). "PPARγ agonists have shown beneficial effects in anti-lung cancer, including disruption of tumor metabolic homeostasis, promotion of cell apoptosis, induction of cell cycle arrest, as well as inhibition of cell invasion and angiogenesis." (PMID 38397426, 2024). "Recent clinical data has substantiated the potential of PPARγ agonists as therapeutic agents for lung cancer." (PMID 38397426, 2024). "PPARG exhibits a multifaceted effect in lung cancer by influencing various molecular mechanisms and impacting the entire tumor microenvironment (TME), including noncancerous elements such as immune cells, fibroblasts, adipocytes, and vascular components." (PMID 39201328, 2024). "Evidence for the suppression of CD36 and other components of the PPARγ transcriptional program was observed during the progression of multiple human cancers, including breast, colon, and lung cancers." (PMID 37816052, 2023). "Cannabinol can regulate human metabolism, reduce β-amyloid toxicity and inflammation in rats through PPARG antagonism, and induce apoptosis through PPARG, which has therapeutic effects on liver, cervical, and lung cancers." (PMID 37334066, 2023). "A 2014 study showed that activated PPARγ inhibited lung cancer cell proliferation by metabolic changes." (PMID 37251321, 2023). "Concerning lung cancer, miR-130a and miR-130b have been identified to play a regulatory role in macrophage polarization by inhibiting or downregulating PPARG expression." (PMID 38044948, 2023). "An array of PPARγ ligands can modulate tumour growth and progression by influencing the WNT, MAPK, NF‐kB and TGF‐β signalling pathways in lung cancer cells and stromal cells, in a PPARγ‐dependent fashion." (PMID 37556076, 2023). "PPARγ-regulated transcriptional networks are impaired in several tissues, giving rise to multiple tumor types, including breast, colon, and lung cancer." (PMID 37816052, 2023). "Later, doubts regarding the suggested beneficial effects of PPARγ activation for metastasis inhibition in lung cancer arose." (PMID 35954274, 2022). "Especially PPARG was shown to be activated under hypoxic conditions in correlation with HIF1A in lung cancer and hepatocellular carcinoma." (PMID 36064320, 2022). "Srivastava and colleagues demonstrated, in a lung cancer model, that treatment with the PPARγ agonist pioglitazone triggers a metabolic switch that inhibits pyruvate oxidation and reduces glutathione levels." (PMID 35954274, 2022).
lung carcinoma (continued). "A good study showed that the activation of PPARγ inhibited transforming growth factor β (TGF-β)-induced epithelial mesenchymal transition (EMT) in lung cancer cells." (PMID 35954274, 2022). "When ciglitazone was combined with SR11237, it significantly increased RARβ expression in lung cancer cell lines, which was diminished by a PPARγ-selective antagonist, bisphenol A diglycidyl ether." (PMID 35631448, 2022). "Many studies have shown that PPAR gamma activation can hinder the progress of lung cancer, and PPARG ligand can be used as a potential therapeutic agent for lung adenocarcinoma and PPARG can also effectively treat lung squamous cell carcinoma." (PMID 35585716, 2022). "The mRNA expression levels of PPARγ were observed to be reduced in lung cancer tissues compared to the normal adjacent lung tissues." (PMID 35631448, 2022). "The inducible conditional knockout of PPARγ solely in macrophages reconstituted the beneficial roles of PPARγ ligand activation in lung cancer cell growth and metastasis inhibition." (PMID 35954274, 2022). "A study elucidated that Tro can hamper the growth of lung cancer cells via inducing apoptosis and, at least in part, inhibit cell proliferation in a PPARγ-relevant manner." (PMID 35631448, 2022). "In lung cancer cells, PPARγ-mediated lipid synthesis strongly induces mitochondrial reactive oxygen species stress and contributes to tumor suppression." (PMID 34775964, 2021). "At the protein level, ALDH18A1 and CPT1B were significantly upregulated, and ACADL and PPARG were slightly underexpressed, in the lung cancer group compared to the control group, which were consistent with the results of their corresponding mRNA expressions." (PMID 34970420, 2021). "Of note, an indirect up-regulation of PPARγ has been found in lung cancer, where the CBD-mediated proapoptotic and antiproliferative effect occurs via the up-regulation of Cox2 and prostaglandins production, with consequent PPARγ nuclear translocation." (PMID 31979368, 2020). "Enhanced activity of PPARγ had an inhibition on TGF-β induction of N-cadherin promoter in lung carcinoma cell lines." (PMID 32085795, 2020). "The role of Cox-2 and PPARγ in pro-apoptosis and tumor regression was explored in lung cancer cell lines, demonstrating that cannabidiol induced the upregulation of Cox-2 and PPARγ following a nuclear translocation of PPARγ by Cox-2 dependent PGs." (PMID 32085795, 2020). "Early stage lung cancer exhibited increased peroxisome proliferators‐activated receptor γ (PPARγ)hi macrophages, decreased CD141+ dendritic cells (DCs), and reduced and impaired NK cells." (PMID 33135337, 2020). "Our studies have amply demonstrated that the activation of PPARγ can significantly inhibit the growth of lung cancer and the downregulation of PPARγ activity contributes to lung cancer progression." (PMID 31420013, 2019). "On PPARG treatment, the sub G1 population went up to 5.5%, which further increased to 15.83% in the combination of PPARG with radiation clearly suggesting the potential of this combination against resistant lung cancer cells." (PMID 31263479, 2019). "In lung cancer, PPARγ inhibits development of primary tumors and metastases in lung cancer, and activation of PPARγ can promote apoptosis." (PMID 31695781, 2019). "Our results highlight the importance of PPARG agonists in improving radiotherapy strategies to treat lung cancer." (PMID 31263479, 2019). "For example, excavatolide B, a diterpene isolated from marine corals, exhibited anti-tumor effects by altering PTEN/Akt and PPARγ signaling pathways in lung cancer cells." (PMID 30018246, 2018). "Meanwhile, synergetic effects of efatutazone and T0901317 on lung cancer cells proliferation inhibition and PPARγ/LXRα/ABCA1 pathway activation were also proved." (PMID 29573196, 2018). "In particular, TRIM25 is overexpressed in breast, colorectal, and lung cancers, while PPARγ is downregulated in these cancers compared with normal tissues." (PMID 30323259, 2018).
lung carcinoma (continued). "Secondly, we demonstrated that PPARγ-sumoylation is evidently involved in lipid metabolism in lung cancer." (PMID 29137280, 2017). "Using these various lung cancer cells, PPARγ-mediated intracellular lipid change was investigated upon TZD treatment." (PMID 29137280, 2017). "In the context of lung cancer, with general agreement on its role as a tumor suppressor, the biological effects of activated PPARγ are perhaps better defined than those of PPARα or PPARβ/δ." (PMID 28316613, 2017). "For example, Cox-2 induction and subsequent Cox-2-dependent activation of PPARγ as a mechanism by which lovastatin lactone induced human lung cancer cell death." (PMID 28678919, 2017). "To that end, we first confirmed PPARγ expression followed by biochemical function of the ligand-activated receptor in a subset of lung cancer cells." (PMID 29137280, 2017). "Here, we report that sumoylation of PPARγ couples lipid metabolism to tumor suppressive function of the receptor in lung cancer." (PMID 29137280, 2017). "We found that ligand activation of PPARγ dramatically induced de novo lipid synthesis as well as fatty acid beta (β)-oxidation in lung cancer both in vitro and in vivo." (PMID 29137280, 2017). "Three PPARs, PPARα, PPARβ/δ, and PPARγ, display distinct biological activities and varied influences on lung cancer biology." (PMID 28316613, 2017). "Certainly, ligand-activation of PPARγ strongly induced mitochondrial ROS level in lung cancer cells." (PMID 29137280, 2017). "A recent study characterized a PPARG anti-proliferative effect in lung cancer that was proposed to be due to the regulation of cellular reactive oxygen species via activation of pyruvate dehydrogenase kinase 4 (PDK4) and beta-oxidation of fatty acids." (PMID 27401066, 2016). "The present study therefore investigates a potential contribution and coordinated action of COX-2 and PPARγ within the lovastatin lactone-induced apoptosis of human lung cancer cells." (PMID 26863638, 2016). "The role of PPARγ in lung cancer extends beyond the regulation of primary tumor formation; mounting evidence suggests that PPARγ activation suppresses tumor metastasis." (PMID 27698657, 2016). "The promising role of PPARγ agonists as therapeutic agents for lung cancer, suggested by experimental studies, has also been documented by clinical data." (PMID 27698657, 2016). "The potential of PPARγ agonists as a novel therapeutic approach in the treatment of lung cancer is thus compelling." (PMID 27698657, 2016). "The role of PPARγ in lung cancer biology is better understood and its potential role as a tumor suppressor is better characterized than those of PPARα or PPARβ/δ." (PMID 27698657, 2016). "These attributes suggest that PPARγ agonists, in combination with other therapies currently in use or in clinical trials, represent a novel, attractive approach in lung cancer therapy." (PMID 27698657, 2016). "This review of the current literature highlights the potential of PPARγ agonists as novel therapeutic modalities in lung cancer, either as monotherapy or in combination with standard cytotoxic chemotherapy." (PMID 27698657, 2016). "In contrast, in lung cancer cells decreasing PDK4 expression both prevented the antiproliferative action of a PPARγ agonist by blocking its action at the G1 → S phase checkpoint and promoted epithelial to mesenchymal transition and chemotherapy resistance." (PMID 26576332, 2015). "Given that PPARγ plays a significant role in anti-inflammatory response, we wanted to test if PPARγ activation inhibits the pro-inflammatory COX2 expression in the lung cancer pathogenesis model." (PMID 26244663, 2015). "In a mechanistic proof-of-principle study, we found that PPARγ sumoylation is important for the anti-tumorigenic effect of TZDs in lung cancer pathogenesis." (PMID 26244663, 2015). "In this regard, a last notable finding from this work was that ligand-mediated sumoylation is critical for anti-tumorigenic function of PPARγ in lung cancer." (PMID 26244663, 2015).
lung carcinoma (continued). "This suggests that ligand-mediated sumoylation of PPARγ plays an important role in lung cancer pathogenesis by modulating prostaglandin metabolism." (PMID 26244663, 2015). "In NSCLC cell lines, activation of PPARγ inhibits cell growth, and in murine models, PPARγ over-expression prevents lung cancer." (PMID 24840047, 2014). "Consistent with this, the PPARγ-independent signals mediating the effects of PPARγ ligands on gene expression and cell proliferation including lung cancer have been shown in other studies although PPARγ-dependent signals were observed." (PMID 24925061, 2014). "Further study identified PPARγ as a critical target for prostacyclin-mediated lung cancer chemoprevention." (PMID 24852754, 2014). "We believe these findings indicate PPARγ in the tumor microenvironment, and in particular TAMs, plays a critical role in lung cancer metastasis." (PMID 22934105, 2012). "While recent work demonstrates PPARγ ligands have beneficial PPARγ-dependent and -independent properties in treating malignancies, emerging insights into PPARγ-independent functions in lung cancer are highlighted here." (PMID 22778711, 2012). "Here, we review the available data that implicate PPARγ in lung carcinogenesis and highlight the challenges of targeting PPARγ in lung cancer treatments." (PMID 22934105, 2012). "Collectively, these data suggest that the PPARγ pathway is a potential target for treatment of lung cancer." (PMID 22934105, 2012). "In lung cancer, decreased expression of PPARγ was correlated with poor prognosis in samples from human lung tumors." (PMID 22934105, 2012). "In this study, knockdown of PPARγ with shRNA or treatment with the PPARγ antagonist T0070907 blocked murine lung cancer cell invasion." (PMID 22934105, 2012). "But Rosiglitazone was found to suppress human lung carcinoma cell growth through PPARγ-dependent and PPARγ-independent signal pathways." (PMID 23046449, 2012). "Agents that selectively activate PPARγ in epithelial and cancer cells would therefore be very attractive for the prevention and treatment of lung cancer." (PMID 22934105, 2012). "Collectively, these studies suggest that increased PPARγ signaling can also serve as a tumor promoter in lung cancer." (PMID 22934105, 2012). "Collectively, these studies suggest that selective activation of PPARγ in NSCLC cells is protective against lung cancer initiation, progression, and metastasis." (PMID 22934105, 2012). "In contrast to lung cancer, a survey of various tumors revealed that PPARγ is generally overexpressed in liposarcoma, colon, breast, and prostate carcinomas." (PMID 22934105, 2012). "Thus, PPARγ expression may serve as a prognostic marker in lung cancer and polymorphisms in the PPARγ gene may be a way to identify patients with increased risk for lung cancer." (PMID 22934105, 2012). "Most previous studies were carried out on lung carcinoma cells or immortalized cell lines, or in animal models of growing lung cancers, and described PPARγ agonists as inhibitors of lung oxidative stress and cell-cycle progression." (PMID 21664456, 2011). "PPARγ expression is highly up-regulated in lung cancers and has been suggested as a potential marker for lung cancer." (PMID 21664456, 2011). "MAPKs, in particular ERK1/2, have been shown to be involved in mediating PPARγ action in mouse myoblast cells and lung carcinoma cells." (PMID 21664456, 2011). "The goal of our study was to determine the effect of systemic PPARγ activation on lung cancer progression and metastasis using the TZD pioglitazone in our orthotopic immunocompetent model." (PMID 22145026, 2011). "For example, a number of studies have suggested anti-estrogen therapy as a lung cancer therapeutic, and in a mouse lung cancer study, the use of a PPARγ agonist had a synergistic effect in reducing tumor burden when used with cis-platinum." (PMID 21179495, 2010).